VIM (vimentin)
Diseases named in the same sentence as VIM in open-access papers (continued):
Sharing a sentence is not in itself a finding about the gene and the disease.
endometriosis (29 papers, 2009 to 2025). The growth of functional endometrial tissue in anatomic sites outside the uterine body. "Increased vimentin expression has been observed in epithelial cells of peritoneal lesions and deep infiltrating endometriosis, suggesting a role in EMT-associated structural changes." (PMID 40806587, 2025). "Repeated genes associated with P-phase (ACTB, ANXA4, BPIFB1, EPHX1, MUC5B, PRDX2, and VIM) could indicate stronger genetic causes associated with pathophysiology of endometriosis." (PMID 32474803, 2020). "The insignificant change in vimentin expression was also seen in deep endometriosis; however, we saw upregulated vimentin expression in ovarian endometriosis compared to healthy endometrium." (PMID 40135061, 2025). "We investigated the expression of EMT markers (E-cadherin and vimentin) in women with endometriosis." (PMID 38513352, 2024). "Immunohistochemical staining for E-cadherin, vimentin, and Masson’s trichrome staining of sections of ectopic lesions from a mouse model of endometriosis proved that the tissue used was endometriosis." (PMID 38795132, 2024). "In our study, we found that E-cadherin was increased and vimentin was reduced in the endometrium of patients with endometriosis, indicating that EMT was blocked during mid-secretory transformation in endometriosis." (PMID 38513352, 2024). "Vimentin, beta-actin, and the ATP synthase subunit were differentially expressed between endometriosis sera and normal sera, warranting further investigation in order to elucidate their role in endometriosis pathophysiology." (PMID 38275362, 2023). "Cytoskeleton proteins, such as actin and vimentin, are upregulated in proteomics samples of endometriosis patients and in eutopic endometrium samples." (PMID 38275362, 2023). "All positively identified lesions were immunopositive for Vimentin, a mesenchyme marker, indicating the presence of endometrial-like stromal cells in lesions collected from all four models of endometriosis." (PMID 34382636, 2021). "Purely stromal, mixed, or poorly differentiated lesions, especially, showed additional cytokeratin-positive stromal cells, whereas epithelial cells of endometriosis with mixed or poor differentiation increasingly expressed mesenchymal markers (vimentin, SMA)." (PMID 32110695, 2017). "The results were in line with previous evidences that E-cadherin was downregulated, while N-cadherin and vimentin were upregulated in endometriosis." (PMID 27034956, 2016). "EMT is now well-documented in endometriosis, featuring decreased E-cadherin expression but increased vimentin expression in the epithelial component of endometriotic lesions." (PMID 27062244, 2016). "The coexpression of keratin and vimentin, shown by immunostaining, indicated that endometriosis lesions had been established in the mice." (PMID 24520268, 2014). "Furthermore, the endometriosis lesions were positive for cytokeratin (epithelium) and vimentin (stroma), consistent with standard endometrial staining." (PMID 41158459, 2025). "However, in women with endometriosis, E-cadherin expression was upregulated, and vimentin was decreased in the mid-secretory phase compared to women without endometriosis." (PMID 38513352, 2024). "Vimentin is closely related to the occurrence and development of various tumors by modulating the EMT, as well as to oncologic settings; data from literature describe EMT as a physiopathological mechanism implicated in endometriosis cells." (PMID 38275362, 2023). "Using endometriotic lesions obtained from patients with severe endometriosis (n = 3), dual staining for IL-33 with cytokeratin (epithelial cell marker) and vimentin (stromal cell marker) revealed that IL-33 colocalizes with both stromal and epithelial cells in the lesion microenvironment." (PMID 34699382, 2021).
endometriosis (continued). "In a subset of 32 patients (13 controls and 19 women with endometriosis), PF was fixed, processed and thinlayers were prepared and stained with Papanicolaou method and with immunocytochemistry using monoclonal antibodies against cytokeratin 7(CK 7), CK 8/18, Ber-Ep4, vimentin, calretinin and CD68." (PMID 19878540, 2009). "Compared with the control group, some genes known to promote the development of endometriosis were decreased in the si-hsa_circ_0063526 agomir group, including MAPK-14, K-ras, N-cadherin, Vimentin, ER-α, ER-β (P < 0.05)." (PMID 34967761, 2021). "The genes with increased expression (KRT18, KRT19, VIM, and NANOG) were then used in subsequent analyses as “endometriosis confirmatory genes”." (PMID 31717910, 2019). "In parallel with the predecidua changes, various CEC types isolated from patients with endometriosis in our cohort showed different gene expression profiles, represented by typically elevated gene expression of KRT18, NANOG, and VIM or of KRT19 and ESR1." (PMID 31717910, 2019). "In the human endometriosis cell lines End1/E6E7 and Vk2/E6E7, FC counteracted estradiol-induced EMT by restoring E-cadherin levels and reducing the expression of N-cadherin, Slug, Snail, and vimentin." (PMID 40806587, 2025). "Similarly, endometriosis stromal cell lines that are cytokeratin-negative and vimentin-positive have been established and used to study epithelial-stromal interactions." (PMID 41158459, 2025). "In our study, we found the enhanced expression of mesenchymal markers (e.g. vimentin) and decreased expression of epithelial markers (e.g. E-cadherin) in eutopic and ectopic endometria of endometriosis, confirmed the involvement of EMT as an important factor that participated in the endometriosis." (PMID 31903498, 2020). "All primary cultures derived from either control eutopic endometrium and endometriosis lesions were positive for endometrial stroma cell markers CD10 and vimentin and negative for endothelial (PECAM1) and epithelial (EPCAM) markers, indicating they represent the endometrial stromal cell compartment." (PMID 38203610, 2023). "To gain further insight into the adipocyte cell proliferation and metabolism in subcutaneous fat from patients with and without endometriosis, we assessed the cultured adipocytes for expression of PCNA, a marker of cell proliferation, and for vimentin and DAPI simultaneously." (PMID 30982470, 2019).
diabetes (28 papers, 2014 to 2026). "The presence, in vivo, of vimentin in islet cells has been considered to represent a state of dedifferentiation with loss of cellular identity associated to diabetes." (PMID 29360826, 2018). "The POLE group had the highest number of cases, characterized by features such as LVSI, large tumor size, higher ASA score and BMI, variable PD-L1 expression (1–>10 %), diabetes mellitus, and positivity for β-catenin, HNFβ, and vimentin." (PMID 41536692, 2026). "Experimental models of diabetes have demonstrated a significant increase in vimentin expression following 2 to 6 months of diabetes." (PMID 39768141, 2024). "The same observation was made for vimentin at 12 and 24 weeks after diabetes induction (P = 0.002, P = 0.001, respectively)." (PMID 37391399, 2023). "MYH9, ERBB2, TCF4, VIM (vimentin), LRRK2 and CAV1 have been implicated as a principal mediator of diabetes mellitus." (PMID 36837510, 2023). "Vimentin protein plays a key role in AT plasticity, and has also been found to be involved in obesity and diabetes." (PMID 36142750, 2022). "Diabetes was associated with significantly increased myocardial expression of collagens type I and type III as well as vimentin, a well-known marker of EMT and EndMT." (PMID 34639160, 2021). "Diabetes also more significantly upregulated the number of Vimentin positive Müller glia cells in WT diabetic mice, as compared to diabetic Fpr2−/− mice (data not shown)." (PMID 33089077, 2020). "Immunohistochemical staining of the airways indicated that Zo1 (an epithelial biomarker) was downregulated and vimentin (a mesenchymal biomarker) was upregulated in rats with diabetes or COPD, and the combination of both diseases amplified these effects." (PMID 32369442, 2020). "The immunofluorescence result showed that both GFAP and vimentin were co-localised with GS in 4-month diabetic rat retinas, indicating the activation of Müller cells in diabetes." (PMID 30401898, 2019). "The expression of vimentin was also increased with increasing duration of diabetes; it was approximately 1.23-fold (at 4 months, n = 6, p = 0.0001) and 1.26-fold (at 6 months, n = 6, p = 0.0001) of that in the normal control group." (PMID 30401898, 2019). "HIF-1alpha, VEGF and GFAP started to increase at 1 month and vimentin at 4 months after diabetes onset." (PMID 30401898, 2019). "PSMD3, a subunit of RNA polymerase, can induce the expression of Cox2, S100A4/FSP-1 and vimentin genes in renal, which contributes to diabetes-mediated chromatin turnover and promotes transcriptional changes in diabetic kidneys." (PMID 30521536, 2018). "POLR2A, a subunit of RNA polymerase II (Pol II) can induce the expression of Cox2, S100A4/FSP-1 and vimentin genes in renal, which contributes to diabetes-mediated chromatin turnover and promotes transcriptional changes in diabetic kidneys." (PMID 30521536, 2018). "IL-22 suppressed diabetes-induced glomerular and interstitial fibrosis as indicated by reduced fibronectin, collagen IV, vimentin and α-SMA expression in kidney tissue lysates." (PMID 28726774, 2017). "Retinal immunoreactivity for GFAP and vimentin were analyzed at 6 weeks of diabetes in animals housed in SE or EE." (PMID 25004165, 2014). "In addition, we identified a more clearly separate vimentin-positive population in chronic pancreatitis, with a higher proportion of these cells in those with pre-diabetes." (PMID 39836539, 2025). "The proportion of islets containing α-cells with filamentous vimentin staining was highly variable in CF donors surviving beyond the first week of life in the presence (0–82% of islets) or absence (0–90% of islets) of known diabetes." (PMID 39836539, 2025). "Interestingly, the treatment with MDL 72527 significantly decreased the diabetes-induced upregulation of vimentin expression in the retinas (p < 0.01)." (PMID 39768141, 2024).
diabetes (continued). "Moreover, they come to the very bold conclusion that vimentin is central to linking obesity with diabetes—this statement needs to be validated carefully." (PMID 35454311, 2022). "EMT and the TGF-β/Smad pathway were activated in the AECs of rats with COPD or diabetes, and the combination of COPD and diabetes amplified those effects, as indicated by downregulation of Zo1 and upregulation of vimentin, TGF-β and Smad4 in immunohistochemical experiments." (PMID 32369442, 2020). "The expression of factors such as HIF-1alpha, VEGF, EPO, EPOR, GFAP and vimentin, was up-regulated with the progression of diabetes in the diabetic rat retinas compared to the expression in normal control retinas, whereas the expression of GS and GLAST was down-regulated." (PMID 30401898, 2019). "In a single previously published case series, vimentin/glucagon and vimentin/insulin co-staining were seen in deceased organ donors with and without type 2 diabetes, with higher numbers of co-expressing α-cells than β-cells and higher numbers of both altered phenotypes in diabetes." (PMID 39836539, 2025). "Diabetes-induced changes in neuronal-specific class III tubulin (Tuj-1), synaptophysin, glutamine synthetase, and vimentin were attenuated in response to SMOX inhibition." (PMID 39768141, 2024). "Rats with diabetes, COPD or both exhibited worse airway epithelial function, greater vimentin expression and lower Zo1 expression than control rats, indicating that the EMT was activated in type 2 diabetes and COPD." (PMID 32369442, 2020). "Post-mortem pancreatic sections from 24 people with CF and 10 organ donors without CF or diabetes were stained for insulin/glucagon/vimentin and Sirius red/fast green with collagen distribution assessed semi-quantitatively and quantitatively (non-CF)." (PMID 39836539, 2025). "In individuals with CF living beyond the first week of life, there was a wide variability in the percentage of islets, including vimentin protein-expressing cells in those with and without known diabetes." (PMID 39836539, 2025). "Four genes (TNFRSF12A, MAP1B, EZR and YWHAZ) upregulated in donors with chronic pancreatitis were also upregulated in vimentin-positive α-cells in donors without diabetes or CF." (PMID 39836539, 2025). "Analysis of existing single-cell RNA-sequencing datasets (three adult donors without diabetes and nine with chronic pancreatitis) for α-cell vimentin expression was performed." (PMID 39836539, 2025). "A trend towards a correlation between donor age and the proportion of islets containing vimentin-positive α-cells was seen in donors without CF or diabetes (r = 0.608; P = 0.062) and in all donors studied with and without CF (r = 0.343; P = 0.047)." (PMID 39836539, 2025). "The expression of vimentin in pancreatic endocrine cells was further interrogated through single-cell RNA-sequencing (RNA-seq) analysis in donors without diabetes and with pancreatic fibrosis secondary to chronic pancreatitis." (PMID 39836539, 2025). "Vimentin-expressing α-cells were also present in a proportion of islets in all cases within a comparator cohort of deceased organ donors without diabetes or clinically evident pancreatic exocrine disease." (PMID 39836539, 2025). "While we were unable to examine changes in vimentin expression in diabetic retinas through immunofluorescence, the data we gathered provided compelling evidence of the impact of SMOX inhibition on glial cell health in the context of diabetes." (PMID 39768141, 2024). "In this study, we examined a range of EMT markers (including vimentin, α-SMA, and collagen I) in diabetic kidneys to investigate whether SKI and ROS can alleviate renal tubular EMT." (PMID 34408650, 2021). "We observed higher positive CD11b and vimentin cells in diabetic mice (group 3 and group 4) than in the non-diabetes group (group 1 and 2)." (PMID 30308936, 2018).
diabetes (continued). "Dividing donors into those without diabetes and those with pre-diabetes (HbA1c >39 mmol/mol (5.7%) and/or fasting blood glucose >5.6 mmol/L)) revealed a higher proportion of vimentin-positive α-cells in pre-diabetic (PD) (46%) than in non-diabetic (ND) (32%) donors." (PMID 39836539, 2025). "IHC pictures of tumor tissue sections from the flanks of the nude mice demonstrated that diabetes mice upregulated BMP4, Vimentin and N-cadherin expression but downregulated E-cadherin expression compared to the control group, revealing that IR may induce BMP4 to medicate the EMT of CRC." (PMID 37370018, 2023). "Our study elucidated that HG induced Golgi stress was mediated by NLRP3/Vps35/Golph3/Vimentin pathway, inhibition of NLRP3 and Golph3 by selected molecular inhibitors zafirlukast and bromocriptine could suppress neuro-inflammation and Golgi stress thus ameliorate diabetes cognitive decline." (PMID 36378718, 2022). "We performed insulin/glucagon/vimentin and SRFG staining in sections from ten organ donors without CF, diabetes or established chronic pancreatitis." (PMID 39836539, 2025).
leiomyosarcoma (28 papers, 2010 to 2026). An uncommon, aggressive malignant smooth muscle neoplasm, usually occurring in post-menopausal women. "Histopathological features as well as the immunohistochemical results, positive for vimentin, actin, myosin and desmin, confirmed the mesenchymal origin and the myoid phenotype of both testicular tumours supporting the diagnoses of leiomyosarcoma." (PMID 37525233, 2023). "Pathological examination and the immuno histochemical profile positive for anti-vimentin antibody and anti-actin were consistent with the diagnosis of leiomyosarcoma." (PMID 28154642, 2016). "Usually, leiomyosarcoma stains positive for vimentin and smooth muscle actin, and they typically express desmin." (PMID 27580598, 2016). "The pathognomonic findings of leiomyosarcoma are spindle-shaped tumor cells with positive markers for smooth muscle cells, vimentin, muscle actin, alpha-smooth muscle actin, and desmin." (PMID 23509466, 2013). "A transthoracic needle biopsy yielded a diagnosis of leiomyosarcoma, and tumor cells were strongly and uniformly positive for vimentin, a smooth muscle actin at immunohistochemical analysis." (PMID 22480303, 2012). "Histopathology of leiomyosarcoma reveals spindle tumor cells, which are positive for markers of smooth muscle activity including vimentin, muscle actin, alpha-smooth muscle actin, and desmin." (PMID 20178598, 2010). "In the cases presented, the fact that negative staining of the tumor with thyroglobulin, TTF-1, and keratin, and that positive staining was observed with vimentin and actin in the first case specimen, led to the immunohistopathological diagnosis of leiomyosarcoma." (PMID 27080750, 2016). "Therefore, we again performed IF staining of tumor sections to examine the expression of leiomyosarcoma markers, including vimentin, α–smooth muscle actin (α-SMA), caldesmon, and desmin, at the xenograft site, with the detected signals supporting these as leiomyosarcoma." (PMID 38451719, 2024). "Immunostaining with vimentin may also be positive for leiomyosarcomas." (PMID 26788392, 2015). "Preoperative biopsy revealed spindle-cell proliferation consistent with leiomyosarcoma (SMA +, Vimentin +, Ki-67 60 %)." (PMID 42262152, 2026). "Another tumor (11.1%) was positive for SMA and interpreted as a leiomyosarcoma, while the other six (66.7%) tumors were negative for all tested antibodies except vimentin." (PMID 38612342, 2024). "One tumor in the study was only positive for vimentin and SMA and diagnosed as a leiomyosarcoma, although a fibroblastic tumor with myofibroblast reaction could not be discarded." (PMID 38612342, 2024). "In contrast, leiomyosarcoma is negative for KIT mutations and mostly positive for desmin, SMA, h-caldesmon, and vimentin." (PMID 38993816, 2024). "Biopsies from the growth showed leiomyosarcoma with tumor cells immunopositive for vimentin, h-Caldesmon, and smooth muscle actin and negative for pan-cytokeratin." (PMID 37711471, 2023). "Silencing the SNAI2 gene could significantly upregulate the expression of CDH1, downregulate the expression of vimentin and CDH2 in leiomyosarcoma cells, and significantly impair the proliferation and invasiveness of cells." (PMID 31749661, 2019). "Immunohistochemically, leiomyosarcomas are nearly uniformly positive for smooth muscle actin, desmin, and vimentin and negative for calretinin, carcinoembryonic antigen, cytokeratin, leukocyte common antigen, neuroendocrine filament, CD-117, and S-100 protein." (PMID 22480303, 2012). "HHF 35, αSMA, Vimentin, Desmin, H-Caldesmon positivity in the low to high grade Leiomyosarcoma component, while the dedifferentiated component may not show any of the myogenic marker reactivity." (PMID 36777814, 2023).
leiomyosarcoma (continued). "The last case showing exclusively spindle cell morphology reveals intense and diffuse reaction for vimentin and smooth muscle actin, with only focal-positive expression for desmin; CKs and CD10 are negative and, therefore, based on this immune profile, this tumour is diagnosed as leiomyosarcoma." (PMID 29182526, 2017). "Immunohistochemical staining of spinal leiomyosarcomas showed positive expression of tumor cell SMA and vimentin, negative expression of CD34 and EMA, and focal weakly positive expression of the S-100 protein." (PMID 36520263, 2022). "The spindle cells are positive for EMA, calretinin, cytokeratin, and vimentin, but negative for smooth muscle actin, S100, and CD117 ruling out leiomyosarcoma, MPNST, and GIST, respectively." (PMID 33520482, 2020). "In leiomyosarcoma, tumor cells are positive for α-SMA, desmin, and vimentin and negative for cytokeratin, epithelial membrane antigen, and S-100." (PMID 26380169, 2015).